CDK4 (cyclin dependent kinase 4)
Diseases named in the same sentence as CDK4 in open-access papers (continued):
Sharing a sentence is not in itself a finding about the gene and the disease.
breast cancer (continued). "In this review, we compile the most recent preclinical and clinical evidence concerning the application of CDK4/6i in breast cancer and elaborate on the treatment strategies, and advantages of these agents for different patient populations." (PMID 38409585, 2024). "In the absence of ligand, AHR complexed with cyclin D and the cyclin-dependent kinases CDK4/6 to promote cell cycle progression in human breast cancer cells." (PMID 38982523, 2024). "The combination of ADCs with CDK4/6 (cyclin-dependent kinase 4/6) inhibitors is an area of research interest in breast cancer treatment." (PMID 39093344, 2024). "In conclusion, amplification of CCND1 and overexpression of cyclin D1 are key in many breast cancers, making CDK4/6 inhibitors like abemaciclib, palbociclib, and ribociclib effective treatments." (PMID 38256428, 2024). "We conducted a retrospective analysis of patients diagnosed with advanced breast cancer between 2018 and 2023 who received treatment with CDK4/6i and underwent locoregional radiotherapy." (PMID 39065777, 2024). "Cyclin D1WT bound CDK4 in mammalian two-hybrid assays in MCF7 breast cancer cells (P < 0.001) and 293 T cells." (PMID 38191593, 2024). "Clinically, this principle has proven effective, as seen in the case of PIK3CA-AKT pathway vulnerability in CDK4/6 inhibitor-treated hormone receptor (HR) + breast cancer." (PMID 39501277, 2024). "These limitations highlight the need for further research in order to fully understand the implications of CDK4/6 inhibitors in varying contexts of breast cancer treatment." (PMID 38992220, 2024). "By increasing the inhibitory effects of RB1 on tumor proliferation, CDK4/CDK6 inhibitors have demonstrated efficacy in cancers such as breast cancer." (PMID 39664374, 2024). "Our findings demonstrated that onvansertib synergizes with alpelisib in PIK3CA-mutant HR+ breast cancer cell lines and patient-derived xenografts that are resistant to ET and cyclin-dependent kinase 4/6 inhibitors." (PMID 39409880, 2024). "In this study, we investigated the effectiveness of the targeted cancer medication CDK4/6 inhibitors, in patients with breast cancer." (PMID 38730711, 2024). "This trend aligned with in vivo assays, in which tumor growth in HR+/HER2-low breast cancer xenografted mice administered CDK4/6 inhibitor combined with endocrine therapy exhibited decreased efficacy relative to the HR+/HER2-0 subtype (P < 0.05)." (PMID 39730704, 2024). "Having found that the depletion of our top targets generated resistance to palbociclib, we further explored the clinical translatability of our genes to predict the sensitivity of mammary tumors to CDK4/6 inhibitors." (PMID 38831405, 2024). "PI3K pathway activation is also involved in both primary and acquired resistance of breast cancer cells to CDK4/6 inhibitors." (PMID 38396649, 2024). "We conducted an umbrella review to explore the impact of CDK4/6 inhibitor combined with ET on breast cancer by summarizing and assessing the meta-analysis (MA) and systematic review (SR) evidence." (PMID 38240835, 2024). "The present study is a retrospective analysis of data from patients with metastatic HR+/HER2- breast cancer who were treated with CDK4/6 inhibitors at a tertiary care institute in Eastern India between 2015 and 2022." (PMID 38344632, 2024). "Combined CDK4/6 inhibitor (CDK4/6i) and endocrine therapy significantly improve the outcome of patients with advanced estrogen receptor-positive (ER+) breast cancer." (PMID 39931212, 2024). "RB1 is a cell cycle regulator, implicated in coordinating multiple pathways leading to the disease progression of ER+ breast cancer and is related to the CDK4/6 activity—RB dependency integrated signature." (PMID 39031010, 2024). "Cyclin‐dependent kinase 4/6 inhibitors (CDK4/6is) are widely used in breast cancer and other cancer types." (PMID 39136283, 2024).
breast cancer (continued). "With the expansion of CDK4/6is for the treatment of breast cancer, the balance between efficacy and safety has become critical." (PMID 38633610, 2024). "This compound provides durable control over tumour growth and has shown promise in overcoming resistance to CDK4/6 inhibitors in breast cancer." (PMID 39270064, 2024). "At the same time, studies have found that CDK4/6 inhibitors inhibit the proliferation of Treg cells by inducing the secretion of IL‐29, IL‐28a and IL‐28b from senescent breast cancer cells, overcoming tumour immune evasion and enhancing anti‐tumour immunity." (PMID 39270064, 2024). "Autophagy and/or senescence induction have been identified in response to most antiestrogen treatments currently being used for the treatment of ER+ breast cancer and are often induced in response to CDK4/6 inhibitors." (PMID 38567308, 2024). "The increasingly significant use of CDK 4/6 inhibitors (CDK4/6i) plus endocrine therapy (ET) in different breast cancer settings has led to clinical trials focusing on this strategy as a primary treatment, with promising results." (PMID 38601755, 2024). "Since large Phase III trials targeted on abemaciclib, palbociclib and ribociclib, CDK4/6 inhibitors are currently considered the best option for treatment-naive patients with HR + advanced breast cancer." (PMID 39161906, 2024). "In conclusion, neratinib enhanced the efficacy of CDK4/6 inhibitor combined with endocrine therapy in HR+/HER2-low breast cancer." (PMID 39730704, 2024). "This study can guide clinicians and decision-makers in similar economies about the best use of CDK4/6 inhibitors in first-line treatment of HR+/HER2- advanced breast cancer." (PMID 39114308, 2024). "Clinical trials are ongoing in patients with HR+/HER2– advanced breast cancer previously treated with endocrine therapy and CDK4/6 inhibitors." (PMID 38327984, 2024). "Most of these deaths occur in patients initially diagnosed with HR+ breast cancer who succumb to their disease after multiple iterations of endocrine therapies plus adjuvants such as CDK4/6 inhibitors or chemotherapy." (PMID 38567308, 2024). "Patients with advanced HR-positive, HER2-negative breast cancer who received cyclin-dependent kinase 4/6 inhibitors (CDK4/6i) as a first-line treatment experienced extended progression-free survival compared to those treated in subsequent lines." (PMID 39065777, 2024). "A recent study demonstrated that the potential autonomous activation of IFN signalling in ER+ breast cancers led to the CDK4/6 inhibitor resistance." (PMID 38282415, 2024). "CDK6 protein expression has been recently demonstrated to indirectly predict for sensitivity to CDK4/6 inhibition in ER+ breast cancers, non-small cell lung carcinomas, colorectal carcinomas, and superficial spreading melanomas." (PMID 38066089, 2024). "A well-known example is the recently approved triplet therapy for ER+/HER2- breast cancer, which includes a CDK4/6 inhibitor, a PI3K/AKT/mTOR inhibitor, and endocrine therapy." (PMID 39501277, 2024). "The patient previously received taxanes, capecitabine, and doxorubicin due to breast cancer progression while receiving hormonal therapy plus a cyclin-dependent kinase 4 and 6 (CDK4/6) inhibitor." (PMID 39099917, 2024). "Currently, there is a clinical trial of patients with ER+ breast cancer treated with a combination of three FDA-approved CDK4/6 inhibitors and anti-PD-1/PD-L1 inhibitors (NCT03294694, NCT02778685 and NCT03147287)." (PMID 38822443, 2024). "The combination of endocrine therapy and CDK4/6 inhibitors such as palbociclib is an effective and well-tolerated treatment for estrogen receptor–positive (ER+) breast cancer, yet many patients relapse with therapy-resistant disease." (PMID 37801608, 2024).
breast cancer (continued). "At present, we anticipate the results of prospective phase II studies regarding a combination of CDK4/6i treatment and RT in specific breast cancer patients populations: CLEAR trial (NCT03750396), ASPIRE trial (NCT03691493), and PALATINE trial (NCT03870919)." (PMID 39120877, 2024). "In conclusion, both endocrine-sensitive and endocrine-resistant HR + /HER2- breast cancer patients with BM can benefit from CDK4/6i treatment." (PMID 38409585, 2024). "The ongoing clinical trials in which CQ or HCQ are combined with antiestrogens and CDK4/6i’s are critical and should better define a role for autophagy in breast cancer survival." (PMID 38567308, 2024). "The inhibition of CDK4 expression by ellagic acid inhibits the proliferation of breast cancer, so ellagic acid is expected to replace CDK4 inhibitors in the treatment of TNBC." (PMID 38476024, 2024). "RET overexpression appears to contribute to resistance to combined CDK4/6i and endocrine therapy in ER+ breast cancer by promoting cell cycle progression at the mitotic phase." (PMID 39931212, 2024). "The introduction of CDK4/6i has significantly advanced the therapeutic landscape for HR+ breast cancer." (PMID 38409585, 2024). "In this study, we perform an unbiased quantitative high-throughput combinatorial screening (qHTCS) to identify compounds capable of overcoming resistance to CDK4/6i in breast cancer cells." (PMID 38961064, 2024). "These subtypes have shown prognostic value in patients with early-stage and metastatic HR+/HER2- breast cancer and predict response to endocrine therapy in combination with CDK4/6 inhibition in patients with metastatic HR+/HER2- breast cancer." (PMID 38992028, 2024). "CDK4/6 inhibition was most effective in suppressing breast cancer cell lines that represented hormone receptor-positive (HR+), luminal-type mammary carcinomas." (PMID 38983782, 2024). "Anomalous activation of CDK2 has been recognized as a primary mechanism of resistance to CDK4/6 inhibition in hormone-receptor-positive (HR+) breast cancer." (PMID 39404419, 2024). "Despite these limitations, this meta-analysis represents the most comprehensive and up-to-date assessment of the role of CDK4/6 inhibitors in adjuvant and neoadjuvant therapy for early breast cancer." (PMID 39329126, 2024). "Cyclin-dependent kinase 2 (CDK2) is thought to play an important role in driving proliferation of certain cancers, including those harboring CCNE1 amplification and breast cancers that have acquired resistance to CDK4/6 inhibitors (CDK4/6i)." (PMID 38047585, 2024). "PR and ER are key prognostic biomarkers, defining hormone-positive breast cancer and its response toward systemic hormonal therapy and/or innovative target therapy as cyclin-dependent kinase 4/6 inhibitors." (PMID 39195292, 2024). "In this way, CDK4/6 inhibitors represent an ongoing strategy in combatting metastatic breast cancer; optimizing primary breast cancer treatment in order to prevent metastasis development." (PMID 38542380, 2024). "Our findings suggest that while both CDK4/6 inhibitors effectively modulate key biological pathways in HR+/HER2- breast cancer, nuances in their impact, particularly on the HER2-enriched signature, warrant further investigation." (PMID 38992220, 2024). "This study further utilized a triple combination approach including neratinib, CDK4/6 inhibitor, and endocrine therapy, to assess the impact of HER2 on the efficacy of CDK4/6 inhibitor combined with endocrine therapy in HR+/HER2-low breast cancer." (PMID 39730704, 2024). "The standard therapy for hormone-receptor-positive, human epidermal growth factor receptor 2-negative advanced breast cancer includes the use of cyclin-dependent kinase 4/6 inhibitors (CDK4/6i) with endocrine therapy." (PMID 39199665, 2024).
breast cancer (continued). "Our findings demonstrate that patients with HR+/HER2-breast cancer treated with CDK4/6 inhibitors experienced a significantly higher incidence of both all-grade and grade 3 or higher nephrotoxic AEs compared to the control group." (PMID 39640578, 2024). "From 2015 to 2022, 24 eligible patients were treated with CDK4/6 inhibitors for metastatic HR+/HER2- breast cancer." (PMID 38344632, 2024). "The pan-PLK inhibitor volasertib demonstrated efficacy as a single agent in HR+ breast cancer PDX models resistant to CDK4/6i." (PMID 39409880, 2024). "Our findings suggest that the novel combination of alpelisib and onvansertib presents a promising therapeutic strategy and warrants clinical exploration of this regimen for HR+ breast cancer patients progressing on CDK4/6i and ET." (PMID 39409880, 2024). "Low molecular weight inhibitors of CDK4/6, such as palbociclib, ribociclib, and abemaciclib, are currently used in selected cancer diseases (e.g., breast cancer)." (PMID 39598723, 2024). "Secondly, suppression of HER2 gene expression in HR+/HER2-low breast cancer cells resulted in significantly improved efficacy for CDK4/6 inhibitor combined with endocrine therapy." (PMID 39730704, 2024). "In vitro experiments showed that a TROJAN LncRNA sensitized breast cancer organoids to the CDK4/6 inhibitor palbociclib, and a series of methods validated the TROJAN-NKRF-CDK2 axis." (PMID 39253075, 2024). "Within this comprehensive review, we systematically evaluate the utilization strategies of CDK4/6i across various subpopulations of breast cancer and explore potential therapeutic avenues following disease progression during application of CDK4/6i therapy." (PMID 38409585, 2024). "Currently, there is an ongoing observational clinical trial to identify and monitor the resistance to first-line breast cancer treatment with CDK4/6 inhibitors in combination with aromatase inhibitors (NCT04660435, TRIESIAS, Fondazione Sandro Pitigliani)." (PMID 39598723, 2024). "Overall, this study indicates an imperative role for the HER2 pathway in determining the efficacy of CDK4/6 inhibitor combined with endocrine therapy for HR+/HER2-low breast cancer." (PMID 39730704, 2024). "Specific activation of PDK1 in BRCA2 mutation carriers is interesting as this kinase has recently been shown to confer resistance to CDK4/6 inhibitors in ER+ breast cancer cell lines, and inhibitors targeting this kinase are under development." (PMID 38059556, 2024). "This represents the first prospective randomized controlled study demonstrating the benefit of switching to another CDK4/6i in advanced HR + /HER2- breast cancer patients." (PMID 38409585, 2024). "Whatever, ALND not only removed the potential metastatic lymph nodes but also provided decision-making basis for adjuvant CDK4/6 inhibitors treatment for luminal breast cancer." (PMID 39544961, 2024). "Drugs targeting CDK4/6 kinases phenocopying p16 are in use for breast cancer and are being tested for PDAC." (PMID 39123441, 2024). "A novel small molecule PI3K inhibitor, inavolisib, has more than doubled progression-free survival when combined with CDK4/6 inhibitor palbociclib plus fulvestrant in patients with recurrent PIK3CA-mutated, HR–positive, HER2-negative advanced breast cancer." (PMID 38542380, 2024). "With a median progression-free survival (PFS) exceeding 2 years in first-line metastatic patients, indicating long-term use, evaluating the enduring safety of CDK4/6is in breast cancer treatment is imperative." (PMID 38633610, 2024). "This study investigated one of the treatment options for advanced breast cancer patients after they completed standard therapy that combines hormone therapy and specific targeted agents called cyclin-dependent kinase 4/6 inhibitors." (PMID 39199665, 2024). "The first CDK4/6 inhibitor approved for first-line treatment for ER+/HER2− breast cancer treatment was palbociclib after the pivotal PALOMA-1 trial in 2017." (PMID 38279242, 2024).
breast cancer (continued). "CDK4/6 inhibitors (CDK4/6i) show anticancer activity in certain human malignancies, such as breast cancer." (PMID 38424044, 2024). "Although combined antiestrogen therapy (ET) plus CDK4/6 inhibition is a highly effective therapy for HR-positive breast cancer, therapeutic resistance remains a common and poorly understood problem." (PMID 38047585, 2024). "The main clinical problem in endocrine breast cancer therapy is an intrinsic or acquired (secondary) clinical resistance to CDK4/6 inhibitors, including palbociclib." (PMID 39598723, 2024). "The current investigation demonstrated a significant relationship between hsa-miR-23a-5p expression in low HR+/HER2-low breast cancer and neratinib, affecting CDK4/6 inhibitor and endocrine therapy." (PMID 39730704, 2024). "Network meta-analysis (NMA) evidence has partially covered CDK4/6 inhibitors in treatment-naïve HR + breast cancer patients, and the results show that adding CDK4/6 inhibitors to endocrine therapy is an effective choice." (PMID 39161906, 2024). "Using machine learning algorithms on multi-omics data from over 6,000 breast cancer patients, we identified six key genes significantly associated with VM and patient risk scores: EP300, PIK3CA, DMXL1, LS, ABL2, and CDK4." (PMID 39165361, 2024). "Therapeutic agents targeting oncogenic drivers, such as BRAF inhibitors in melanoma and CDK4/6 inhibitors in breast cancer, are currently established as the mainstays of cancer therapy." (PMID 38622197, 2024). "The standard therapeutic choice for advanced HR+ breast cancer includes endocrine therapy in combination with cyclin-dependent kinase 4/6 (CDK4/6) inhibitors." (PMID 38791880, 2024). "Following the findings that CDK4/6 inhibition additionally stimulates the immune response in breast cancer, several treatment strategies combining CDK4/6 and immune checkpoint inhibitors have been explored to boost immune response." (PMID 38927958, 2024). "Collectively, these findings indicated that CDK4/6 inhibitor combined with endocrine therapy is effective in treating HR+/HER2-low breast cancer, but with lower efficacy compared with HR+/HER2-0 breast cancer." (PMID 39730704, 2024). "Addressing this enigma, our innovative approach included knocking down HER2 in HR+/HER2-low breast cancer cells, resulting in a substantial enhancement of the inhibitory effects exerted by the combination of CDK4/6 inhibitor and endocrine therapy." (PMID 39730704, 2024). "CDK4 is a prominent oncogene in breast cancer, and CDK6 is closely related to the differentiation of human hematopoietic stem cells." (PMID 39011505, 2024). "Dalpiciclib, like most selective CDK4/6 inhibitors, was used before in treating various cancers, especially breast cancer." (PMID 39598629, 2024). "In this study, we have discovered a OGT-MITF axis that plays a crucial role in regulating MITF transcriptional activity and conferring resistance to CDK4/6 inhibitors in breast cancer." (PMID 38961064, 2024). "Given the lower expression of TAM/Met in HER2+ breast cancer, as expected, we showed that combined TAM/Met and CDK4/6 inhibition exhibited less efficacy in HER2+ breast cancer lines." (PMID 38927958, 2024). "In accordance with these reported observations, BNIP3(L)-high MCF7 cells also demonstrated drug resistance to Tamoxifen, a FDA-approved drug used in ER(+) breast cancer treatment and Palbociclib, a CDK4/6 inhibitor." (PMID 38834039, 2024). "High expression of the receptor tyrosine kinase REarranged during Transfection (RET) has been associated with resistance to endocrine therapy in breast cancer, but the role of RET in CDK4/6i treatment response/resistance remains unexplored." (PMID 39931212, 2024). "The role of HER2 in modulating the efficacy of CDK4/6 inhibitor combined with endocrine therapy in HR+/HER2-low breast cancer was assessed by silencing HER2 in HR+/HER2-low breast cancer cells." (PMID 39730704, 2024).